CRP (C-reactive protein)
Diseases named in the same sentence as CRP in open-access papers (continued):
Sharing a sentence is not in itself a finding about the gene and the disease.
infection (continued). "On the contrary, although plasma CRP is elevated in almost all of the patients with PUUV infection, high CRP level does not indicate a more severe disease." (PMID 23990945, 2013). "We used selective decontamination of the digestive tract by non-absorbable antibiotics for infection prevention in many of our patients but the use apparently did not confound the value of CRP and PCT [changes]." (PMID 23762396, 2013). "Since WBC was not elevated in patients with higher CRP levels it is unlikely that severe infections were the reason for CRP elevation." (PMID 22292070, 2012). "The validity of positive PCR results not confirmed by BC was suggested by elevated biomarkers of infection, i.e. C-reactive protein (CRP) and procalcitonin (PCT)." (PMID 23029360, 2012). "In conclusion, we suggest that an elevated CRP and a reduced NCLZ : CLZ ratio might help in the differential diagnosis between an overdose and an infection/inflammation induced clozapine toxicity and, therefore, help prompt selection of treatment strategy." (PMID 22934219, 2012). "However, the infection group had significantly higher PCT (P < 0.01), CRP (P < 0.01), and IL-6 (P < 0.01) levels, WBC counts (P < 0.01), and I/T ratio (P = 0.05) than the noninfection group." (PMID 22685675, 2012). "Procalcitonin is superior to CRP in distinguishing infection from non-infective pleural diseases, even when controlled for the level of systemic inflammation." (PMID 23251353, 2012). "Comparison of AUCs for developing infection between the predictors WBC, Mcyt, CRP and Copeptin." (PMID 23118979, 2012). "Significantly higher values between the infection and noninfection groups were seen for CRP, IL-6, WBC, I/T ratio, PCT, and CT." (PMID 22685675, 2012). "Procalcitonin was distinctly superior to CRP, as unlike CRP, procalcitonin was minimally raised in the presence of inflammation without infection." (PMID 23251353, 2012). "The quantitative pooling and a qualitative summary of the results suggested that procalcitonin might be a better discriminatory marker than C-reactive protein (CRP) and that IL-6 had a very good ability to predict documented infection." (PMID 22588015, 2012). "They showed a similar predictive value for future infection compared to WBC and CRP." (PMID 23118979, 2012). "None of the patients was observed to have an infection or inflammation during the observation period, and their CRP and IL-6 values were low (CRP 0.3 ± 0.6 mg/dL, IL-6 5.6 ± 4.0 pg/mL)." (PMID 23193472, 2012). "Surprisingly, we also observed a moderate, but noticeable rise in LBP and CRP plasma levels from day 7 to day 14 in patients of the surviving group without any evidence for a new or recurrent infection." (PMID 21901123, 2011). "These biomarkers, among which C-reactive protein (CRP) is one of the most studied, could be used as surrogates of infection diagnosis." (PMID 21762483, 2011). "Adding increased CRP into the model reduced the accuracy; this is not surprising as CRP is a late rather than early marker of infection." (PMID 21958494, 2011). "Data from the PRRSV-infection experiment were excluded from further analyses due to the evident inability of this infection to induce any protein apart from CRP and therefore not contributing to defining the optimal APPs and APP combinations." (PMID 21414190, 2011). "However, the site of action for the two proteins is likely different: while CRP acts in a systemic manner as an acute phase protein, PTX3 is more likely to act locally upon infection or inflammatory stimuli, e.g. on injured endothelium." (PMID 21915248, 2011). "Any elevation of CRP and IL-6 was thus interpreted to reflect inflammation secondary to benign or malignant biliary disease, rather than infection." (PMID 21970875, 2011). "The failed patient in group A had a fluctuating CRP level, and the infection recurred with a discharging wound during the period without drugs." (PMID 21883049, 2011).
infection (continued). "In our study, the highest CRP value was 26.9 mg/l, and most CRP values were between 0 to 10 mg/l; therefore, in this study, CRP was a biomarker not indicating infection but monitoring disease activity." (PMID 21679442, 2011). "Reports have displayed that CRP levels above 60 mg/l in febrile SLE patients without serositis almost always indicate infection; whereas in SLE alone, CRP levels are only moderately raised even in patients with very active disease." (PMID 21679442, 2011). "Although we did not measure CRP, the study children were free of any clinical infection when blood sampling was done." (PMID 20411676, 2010). "In clinical practice a CRP value of 100 mg/l is often used as a crude cut-off, with a higher figure suggesting a bacterial rather than a viral origin of an infection." (PMID 20626864, 2010). "This can be adjusted with serum C-reactive protein (CRP) levels, a marker of infection." (PMID 20411676, 2010). "These episodes of greatly increased CRP production, which persist as long as the infection is not controlled and eliminated, have no detectable antiinflammatory or immunosuppressive effects." (PMID 20039408, 2010). "In contrast to CRP and WBC, PCT may have one very important potential – it might be a marker for clinically relevant infections and could be used to decide if antibiotic treatment should be initiated or not." (PMID 19594893, 2009). "C-reactive protein (CRP), an acute phase protein, will be analysed at D0 to identify volunteers whose ferritin concentration might be falsely elevated by occult infection or inflammation." (PMID 19149890, 2009). "We use regression models to examine associations of ABI and blood pressure with cholesterol, triglycerides, and body mass index (BMI) (measures of energy balance) and with biomarkers of inflammation [C-reactive protein (CRP)] and infection [erythrocyte sedimentation rate (ESR), leukocytes (WBC)]." (PMID 19668697, 2009). "CRP, even though being nonspecific, has proved to be helpful in establishing the etiology of some infections." (PMID 20011658, 2009). "CRP is not a good predictor for infection among patients presenting septic shock during the early postoperative period." (PMID 20512289, 2009). "In our cohort, PCT on the day of fever was significantly higher in patients with proven infection compared to the previous day value, while CRP was not." (PMID 20028533, 2009). "While all animals typically displayed low CRP levels within normal ranges prior to infection (not shown), at autopsy the non-vaccinated control group showed systemic inflammation by a marked increase in CRP." (PMID 19367339, 2009). "Finally, when compared with body temperature, leukocyte count and CRP, PCT was the most accurate marker of infection." (PMID 19386110, 2009). "Otherwise, in SSc patients, besides elevations due to infection, no significant elevations of CRP levels are seen." (PMID 18439295, 2008). "The PCT level increases transiently, (in opposition to C-reactive protein (CRP) and leucocytes) for only 12–24 hours after surgery, if hvis the patient is not developing an infection." (PMID 18620598, 2008). "Selenium and parameters of infection or inflammation have been recently described as a situation of negative correlation between Se and CRP and IL-6." (PMID 18221503, 2008). "A limitation of this study is that the reliability of PCT was not compared with CRP or other infection markers, such the leukocyte count, because these analyses were not standardised and performed at every biochemical laboratory of the participating hospitals." (PMID 17324267, 2007). "On the fifth postoperative day, CRP levels decreased more significantly (p < 0.01) in patients without infection than others." (PMID 17505683, 2007). "This increase in CRP was significantly greater in the patients with infection than without infection over time: second postoperative day, OR = 17.37, 95% CI: 2.43-124.18; fifth postoperative day, OR = 26.00, 95% CI: 2.98-226.97; p < 0.01." (PMID 17505683, 2007).
infection (continued). "One trial in Tanzania showed no additional effect on markers of infection (C-reactive protein) compared with iron and folic acid." (PMID 17521431, 2007). "Furthermore, specifically for infection, one can see by means of the confidence intervals that there is a statistically significant difference between the PCT ROC curve and the CRP ROC curve." (PMID 18034890, 2007). "An acute-phase protein produced by hepatocytes, C-reactive protein (CRP) has historically been used as a non-specific marker for infection, inflammation or tissue damage." (PMID 17705867, 2007). "PCT levels were higher in systemic than local infection than rejection than no rejection.PCT levels remained within normal limits in patients with acute graft rejection.CRP levels were equally elevated in all groups.WBC count was similar in all groups." (PMID 17038199, 2006). "This would suggest that infection was not the main stimulus to the increased C-reactive protein concentrations." (PMID 12966420, 2003). "Fourth, in most patients fever, fatigue, and the serum CRP elevations recurred following every chemotherapy cycle, which is not suggestive of infection-related fever, and the symptoms and CRP elevations were limited to patients who received raltitrexed." (PMID 12237767, 2002). "However, pre-admission inflammatory biomarkers (e.g., CRP, procalcitonin) and detailed antibiotic administration data were not available for all patients; thus, residual confounding from unmeasured infection activity cannot be ruled out." (PMID 41607470, 2026). "From a practical standpoint, routinely available markers (CRP, PCT, leukocyte-derived indices, albumin, lactate) are the most immediately actionable when interpreted longitudinally to distinguish expected postoperative inflammation from evolving infection and to support early stratification." (PMID 41598637, 2026). "Moreover, being the first, we report that maternal plasma parameters of infection do not translate into higher levels of CRP in HM." (PMID 40507109, 2025). "Therefore, when you see high CRP levels indicating major inflammation, along with an altered PC/MPV ratio that points to a hematopoietic response, it offers a more specific confirmation of an active infection." (PMID 41250763, 2025). "Moreover, CRP, while a sensitive marker of systemic inflammation, is non-specific and can rise in response to global surgical stress, tissue injury, or infection, rather than mechanisms directly related to neuroinflammation and acute cognitive dysfunction." (PMID 41303282, 2025). "Fecal calprotectin may be elevated due to many luminal inflammatory processes, including infection, and CRP may be elevated in patients due to non-intestinal sources of infection or inflammation." (PMID 40589947, 2025). "This aligns with observations from the Pravastatin or Atorvastatin Evaluation and Infection Therapy-Thrombolysis in Myocardial Infarction 22 (PROVE IT-TIMI 22) study, where improved clinical outcomes in patients were associated with reduced CRP levels independent of lipid profiles." (PMID 40440323, 2025). "highlighted possible discrepancies between CRP, procalcitonin, and interleukin-6 (IL-6) in patients with infections, where some people had normal CRP levels but elevated IL-6, indicating that measuring CRP alone might not be reliable in these cases." (PMID 40123598, 2025). "This suggests that CRP levels do not vary significantly based on the type of infection and may not serve as a distinguishing factor among these conditions." (PMID 40727523, 2025). "The authors concluded that increased inflammatory marker levels were possible even without the presence of underlying infection, and elevated preoperative ESR and CRP levels might not be considered a relative contraindication for shoulder arthroplasty surgery." (PMID 40363957, 2025).
infection (continued). "Perioperative antibiotic management is critical; regardless of initial infection markers (e.g.leukocyte count, C-reactive protein) or the results of oxygen/anaerobic cultures from the drainage fluid, all patients should receive prophylactic antibiotics as per standard guidelines." (PMID 40936689, 2025). "However, the laboratory markers of infection, including peripheral blood WBC count, neutrophil percentage, PCT, CRP, peritoneal dialysate WBC count, and the presence of multinucleated cells in dialysate, were significantly elevated in the PDAP group (all p < 0.001)." (PMID 41017908, 2025). "Furthermore, the absence of postoperative complications, such as infections, ensures that the measured CRP kinetics reflect an uncomplicated recovery, thereby strengthening the correlation with the initial surgical trauma." (PMID 41472138, 2025). "However, CRP is a nonspecific marker of inflammation, that is, it is not only elevated in response to infection." (PMID 40313464, 2025). "Elevated CRP emerged as the most consistent marker of infection, although it is not specific." (PMID 40978879, 2025). "Biomarkers such as procalcitonin and CRP help assess infection severity but were not elevated here." (PMID 40995251, 2025). "Subsequently, the patient experienced a progression of the infection on March 19, manifesting as fever with chills (maximum temperature 39 °C), elevated procalcitonin (PCT) (6.85 ng/mL), and decreased white blood cell count (WBC 1.0 × 109/L) and elevated C-reactive protein (CRP 62.62 mg/L)." (PMID 41234929, 2025). "Although elevated urine retinol binding protein to creatinine ratio (uRBP/Cr) and serum C-reactive protein (CRP) may suggest ICI-AIN, other causes such as infection and inflammation, as well as other irAEs, must be ruled out." (PMID 40589793, 2025). "In patients with CSKP infection, the levels of CRP, PCT, and IL-6 in the death group were significantly higher than those in the survival group (p < 0.05), indicating that the values of these three indicators are positively correlated with the severity of the infection." (PMID 39975685, 2025). "As signs and symptoms are nonspecific and difficult to make in a severe burn patient, cytokine storm should be entertained and evaluated for in burn patients who present with signs of organ system dysregulation and have rising TG, ferritin, and CRP, especially in the absence of an obvious infection." (PMID 39820414, 2025). "While several studies established high sensitivity and specificity for CRP, particularly in spinal surgery, other findings suggested that elevated CRP alone may not always lead to earlier infection detection, as seen in colorectal procedures." (PMID 40342430, 2025). "CRP levels may be elevated in patients with cirrhosis regardless of the presence of infection, and paradoxically, they may be lower in advanced liver disease due to impaired hepatic protein synthesis." (PMID 40863214, 2025). "No absolute values of CRP or PCT effectively diagnosed infections." (PMID 41625880, 2025). "Some patients with elevated CRP levels might thus have had a subclinical infection and not chronic disease-related systemic inflammation, and might in that sense be misclassified." (PMID 41294682, 2025). "This persistent, subclinical inflammation, termed “inflammaging”, is characterized by modest but sustained elevations of circulating cytokines such as interleukin-6 (IL-6), tumor necrosis factor alpha (TNF-α), and C-reactive protein (CRP), even in the absence of infection." (PMID 41373468, 2025). "The average CRP value was significantly greater post cannulation compared to pre cannulation suggesting that MCS itself may increase CRP, making it less useful for the detection of new infection on MCS." (PMID 40523137, 2025). "Consequently, we did not exclude individuals that reported any recent infection at blood sampling (n = 446; 9.4%) or those with a CRP level of >10 mg/L (n = 57; 1.2%)." (PMID 40605248, 2025).
infection (continued). "Moreover, traditional markers of infection and organ dysfunction, such as procalcitonin (PCT), C-reactive protein (CRP), or leukocyte count, may be altered by ECMO12." (PMID 41466056, 2025). "However, we also observed overlap: some patients without infections had high CRP values postoperatively (e.g., a few open surgery patients without infection still had CRP ~120–150 mg/L on POD4)." (PMID 41153812, 2025). "The C-reactive protein (CRP) was mildly elevated with no signs of infection." (PMID 41018322, 2025). "Acute phase proteins, like C-reactive protein, are useful but not specific to infection." (PMID 41301983, 2025). "Likewise, neither PCT nor CRP levels were considered to have the ability to predict the onset of infection in our study." (PMID 40416960, 2025). "However, several covariates exhibited more substantial changes, e.g., baseline NEWS (+ 20.0%), culture-negative infections (−46.7%), and CNS infections (+ 13.4%), indicating a more pronounced influence of adjusting for CRP percentile change on these factors." (PMID 40764898, 2025). "Interestingly, surrogates of infection such as CRP and WBC count did not influence antimicrobial prescribing in our cohort." (PMID 41262354, 2025). "CRP POCT offers a potential solution for fast and cost-effective diagnosis, and the results from this study suggest that CRP POCT might be effective in guiding clinicians at hospitals in Zanzibar to use antibiotics more appropriate in childhood infections." (PMID 41433251, 2025). "The challenge is that early postoperative CRP elevations are non-specific—a high CRP in the first 2–3 days after surgery could be entirely due to the surgical trauma rather than infection." (PMID 41153812, 2025). "Normal results of C-reactive protein (CRP) ruled out active systemic inflammation or infection." (PMID 41245494, 2025). "Therefore, for elderly patients with catatonia, clinicians should perform comprehensive pre-admission evaluations, including chest CT, complete blood count, C-reactive protein (CRP), procalcitonin (PCT), and blood urea nitrogen (BUN) to assess infection indicators." (PMID 40160203, 2025). "In patients who developed an infection (n = 61) during hospitalization (median [IQR] serum level of CRP during hospitalization: 73.4), we did not observe any difference in serum levels of LBP or sCD-14 between the favorable and unfavorable outcome groups at any measurement time point." (PMID 39859200, 2025). "CRP’s rapid synthesis in response to inflammatory signalling and its relatively short half-life make it a more responsive biomarker than the WBC count, which may remain normal or fluctuate due to physiological influences unrelated to infection control." (PMID 41556000, 2025). "Nevertheless, it is unclear whether C-reactive protein predicts infection with MDR versus non-MDR pathogens." (PMID 39601576, 2025). "Thus, we can say that the infection can influence significantly the IL-6 and CRP values, but these values are not sensitive to the smoking habit." (PMID 40242671, 2025). "CRP (C-reactive protein) is commonly used, elevated levels may suggest presence of infection, but it is not specific." (PMID 41465792, 2025). "By postoperative Day 24, CRP had increased to 1.06 mg/dL without infection." (PMID 40098608, 2025). "Blood tests may reveal elevated ESR or CRP, which, while commonly associated with ARMD, require cautious interpretation as they do not always indicate infection." (PMID 40017540, 2025). "The patients who did not achieve infection eradication were noted to have a significantly higher preoperative CRP (197.9 ± 120.2 vs. 142.2 ± 98.1 years, p = 0.016) and trend towards a higher ESR (70.5 ± 35.8 vs. 56.0 ± 35.5 years, p = 0.067) but similar albumin levels (p = 0.542)." (PMID 38247607, 2024).